MMP28 (matrix metallopeptidase 28)
Diseases named in the same sentence as MMP28 in open-access papers (continued):
Sharing a sentence is not in itself a finding about the gene and the disease.
tumor (32 papers, 2006 to 2025). "In our study, abnormal hypermethylation of promoter CpG dinucleotides of the MMP2, MMP23B, MMP24, MMP25, and MMP28 was associated with HER2-positive tumor status, and, to a different extent, with CpG island hypermethylated epigenomic BC subtype." (PMID 32397602, 2020). "A subcutaneous graft tumor model was constructed to assess the tumor-promoting effect of MMP28 and its ability to induce M2 TAM infiltration." (PMID 39972459, 2025). "Our previous investigations demonstrated that MMP28 knockdown attenuates the influence of tumor tissue on M2 TAM infiltration in vivo." (PMID 39972459, 2025). "Having determined the pivotal role of EGFR in the tumor promotion of MMP-28, we aimed to elucidate the mechanism by which MMP-28 regulated EGFR." (PMID 39994761, 2025). "Consistent with expectations, in vivo bioluminescence experiments revealed significant inhibition of tumor growth in the MMP28 knockdown group compared with the control group." (PMID 39972459, 2025). "In liver cancer, MMP28 upregulation drives cell migration and invasion, which are correlated with tumor size, vascular invasion, TNM stage, and overall survival." (PMID 39972459, 2025). "Immunohistochemical staining of tumor tissues from both groups revealed significantly lower MMP28 and Ki67 expression levels in the knockdown group than in the control group." (PMID 39972459, 2025). "Given its relatively recent discovery within the MMP family, the regulatory significance of MMP28 in tumor progression is particularly noteworthy." (PMID 39972459, 2025). "MMP28, the most commonly identified MMP, possesses a prototypic MMP domain and is implicated in tumor progression." (PMID 39972459, 2025). "MMP-28 was found in tumor cells, particularly in smaller tumors (<2 cm), and in tumor stroma, MMP-21 was detected in tumor cells." (PMID 40227764, 2025). "Meanwhile, we assessed MMP-28 protein expression level in tumor tissues and corresponding adjacent peri-tumor tissue through immunohistochemistry (n = 14) and immunoblotting (n = 14)." (PMID 39994761, 2025). "The MMP28 was mainly overexpressed in malignant tumor cells and stromal cells, while expression in immune cells was low." (PMID 37821678, 2023). "Further analysis of the correlation between MMP28 expression and patient clinicopathological parameters showed that the higher the histological tumor grade, the higher was the expression of MMP28, implying its involvement in PDAC progression." (PMID 37821678, 2023). "Our current study demonstrated that MMP28 overexpression in tumor tissues was closely related to a poor outcome in PDAC patients." (PMID 37821678, 2023). "Single-cell sequencing analysis showed MMP28 has strong correlations with malignant cells and stromal cells infiltration in the tumor microenvironment." (PMID 37821678, 2023). "The results indicated higher expression levels of MMP28 in stromal and malignant tumor cells compared with immune cells." (PMID 37821678, 2023). "Subgroup analysis demonstrated that the mRNA expression of MMP28 was closely related to tumor grade and, as tumor grade increased, the MMP28 expression level increased." (PMID 37821678, 2023). "More experimental studies are needed to explore the interaction between MMP28 and tumor-related signaling pathways during pancreatic carcinogenesis." (PMID 37821678, 2023). "IHC analysis demonstrates that a reduction in CD36 and MMP28 expression is associated with an increase in E-cadherin expression in tumor lesions with CD36 knockdown, as compared to NTC tumor tissues." (PMID 35008415, 2022). "We found that MMP1, MMP3, MMP7, MMP9–MMP12, and MMP14 were significantly upregulated in tumor tissue, while MMP28 was significantly downregulated in tumor tissue." (PMID 34804973, 2021).
tumor (continued). "We also evaluated the protein level of MMPs in our patients and measured the expression level of MMP1–MMP3, MMP7–MMP9, MMP11, MMP12, MMP14, MMP17, MMP19, and MMP28 in their tumor tissue and adjacent normal tissue by Western blot." (PMID 34804973, 2021). "Among these, RACGAP1, RARRES3, TPX2, MMP28, GPR87, and KIF14 were upregulated and positively associated with poor survival, whereas TSPAN7 was downregulated and identified as a tumor suppressor." (PMID 33033514, 2020). "Among these differentially expressed genes, MMP1, MMP12, MMP13 and MMP28 were consistently reduced in hnRNP K-knockdown cells but elevated in tumor cells." (PMID 24885469, 2014). "MMP28 over expressing N87 (N87-MMP28) xenograft tumors showed a highly invasive pattern in HE staining sections, indicating MMP28 expression significantly promotes xenograft tumor invasion into the surrounding tissue." (PMID 21615884, 2011). "Invasiveness and tumor formation of stable cells overexpressing MMP28 were tested in vitro and in vivo." (PMID 21615884, 2011). "In summary, MMP-2, MT1-MMP and the previously unreported MMP-28 were very highly expressed in tumour samples." (PMID 16465195, 2006). "In summary, MMP-2, MT1-MMP and the previously unreported MMP-28 were very highly expressed in tumour samples while MMPs 1, 7, 9, 11, 15, 19 and 23 were highly expressed." (PMID 16465195, 2006). "In turn, MMP-28 OE promoted tumor growth and shortened the survival of mice in vivo." (PMID 39994761, 2025). "In vivo studies confirmed the critical role of MMP28 in tumor growth and TAM infiltration." (PMID 39972459, 2025). "Compared with the vector control, the overexpression of MMP28 significantly accelerated tumor growth, while the administration of the JNK inhibitor SP600125, the anti-IL-8 antibody MAB208-SP, or the anti-VEGFA antibody MAB293-SP inhibited tumor growth to varying degrees." (PMID 39972459, 2025). "Finally, the patient-derived tumor xenograft (PDX) model confirmed that MMP-28 is a valuable biomarker for Erlotinib therapy." (PMID 39994761, 2025). "We evaluated the tumor-promoting effect of MMP28 in vitro with CCK-8, Transwell, and EdU assay and Western blotting and explored the potential mechanism of MMP28-induced M2 polarization of TAMs with a coculture system, immunofluorescence staining and flow cytometry." (PMID 39972459, 2025). "Specific MMPs, including MMP2, MMP9, MMP11, MMP14, MMP15, MMP25, and MMP28, were increased in this region, indicating their distinct roles in the tumor microenvironment and confirming the importance of understanding the effects of cysteamine on specific MMPs in GBM cancer models." (PMID 38893149, 2024). "The MMP28 may also play a vital role in the PDAC tumor microenvironment by regulating malignant and stromal cells, suggesting that MMP28 may provide novel therapeutic target for PDAC treatments." (PMID 37821678, 2023). "In contrast MMP28, which cleaves casein, was down-regulated in tumour samples (7.3-fold)." (PMID 37397358, 2023). "Others have reported that MMP28 contributes to tumor cell invasion and metastasis." (PMID 33005006, 2020). "MMP28 is expressed in normal and carcinoma tissues, basal keratinocytes at and surrounding wound edges, in fetal tissues and rhesus monkey placenta during early pregnancy, suggesting a role for MMP28 in normal tissue homeostasis, wound repair, and development, as well as in tumor progression." (PMID 21615884, 2011). "Interestingly MMP-28, or epilysin, is very highly expressed in bladder samples, especially in high-grade tumours." (PMID 16465195, 2006). "In addition, MMP-28 KD significantly extended the survival of mice in an orthotopic tumor model." (PMID 39994761, 2025). "In a patient-derived xenograft (PDX) model of PDAC, we analyzed the expression levels of MMP-28 in patients’ serum and PDX tumor tissues, and assessed the tumor’s sensitivity to Erlotinib." (PMID 39994761, 2025).
tumor (continued). "MMP28 facilitates tumor progression via TGF-α/EGFR axis activation, where elevated MMP28 expression enhances TGF-α maturation to drive oncogenic signaling and metastasis." (PMID 40486509, 2025). "Mechanistic studies revealed that MMP28 promotes MAPK/JNK signaling pathway phosphorylation, thereby reshaping the tumor microenvironment." (PMID 39972459, 2025). "Our data show that as we transition from normal tissue to a primary tumor and then metastasis, we see an increase in the expression of both CD36 and MMP28." (PMID 35008415, 2022). "MAPK signalling pathway activated by nicotinic cholinergic receptors (NCRs) can enhance tumour cell proliferation, accompanied by increased expression of MMP2 and MMP28 genes." (PMID 34809653, 2021). "Consistent with the WGCNA results, in the GSE15471 dataset, the TSPOAP1 in the tumor group was significantly lower expressed, while the ADGRG6, GPR87, FAM111B and MMP28 were significantly higher expressed compared with the normal group." (PMID 34809653, 2021). "Among these DE-MTGs, upregulated RACGAP1, RARRES3, TPX2, MMP28, GPR87, and KIF14 with HR > 1 were regarded as oncogenes, whereas downregulated TSPAN7 with HR < 1 was regarded as a tumor suppressor." (PMID 33033514, 2020). "Consistent with the results of integrated analysis, mRNA expression of RACGAP1, RARRES3, TPX2, MMP28, GPR87, and KIF14 was significantly upregulated in PDAC tumor tissues, whereas TSPAN7 was significantly downregulated." (PMID 33033514, 2020). "MMP-28 induces epithelial-mesenchymal transitions (EMT), which yield tumor cells with collagen-invasive properties allowing the invasion of collagen matrices." (PMID 21843314, 2011). "Moreover, since both MMP-28 and TGF-α are secreted proteins, this signaling can be transmitted to neighboring tumor cells via paracrine mechanisms and even affect distal lesions via endocrine actions." (PMID 39994761, 2025). "In a subcutaneous tumor model derived from KPC with MMP-28 KD or not, results demonstrated that MMP-28 KD significantly inhibited tumor growth." (PMID 39994761, 2025). "In addition to the cell-lines, four primary GBM cell cutures, which were derived from patient's tumor samples, were analysed for MMP-1, -8, -9, -10, -11, -13, -17, -19, -23, -24 and MMP-28 mRNA expression by semiquantitative RT-PCR." (PMID 21067565, 2010). "While investigating whether the function of MMP-28 depends on TGF-α, we injected exogenous recombinant TGF-α protein into subcutaneous tumor model derived from KPC cells with or without MMP-28 KD." (PMID 39994761, 2025). "We could see that about half MMPs are highly expressed in tumor tissues as compared with normal tissues, including MMP9, MMP10, MMP11, MMP12, MMP15, MMP25, MMP26 (all, P<0.05), while some other MMPs decreased in tumor tissues, including MMP2, MMP14, MMP16, MMP24, MMP28(all, P<0.05)." (PMID 32669958, 2020). "As MMP28 increased invasion and tumor volume in the absence of altered proliferation, we hypothesize MMP28 may influence expression of other genes related to tumor growth or vascular formation." (PMID 21615884, 2011). "NPC tumor samples compared with adjacent normal tissues, whereas the mRNA levels of MMP13 and MMP28 were not significantly different between the tumor and adjacent normal tissues." (PMID 24885469, 2014).
cancer (27 papers, 2011 to 2025). A tumor composed of atypical neoplastic, often pleomorphic cells that invade other tissues. "Favorable prognosis was observed in patients presenting high expression of “luminal like” genes (AR, GATA3) and decreased survival was observed in patients expressing cancer stem cell-like (WNT11) or EMT-associated genes (MMP28)." (PMID 32708049, 2020). "In addition, a pan-cancer correlation analysis using the TCGA database revealed that MMP-28 expression was a significant risk factor specifically for PDAC." (PMID 39994761, 2025). "After a 48-h incubation period, cancer cell CM (from AsPC-1 and BxPC-3 cell lines) with MMP28 knockdown exhibited a reduced capacity to attract TAMs compared with that of the control group." (PMID 39972459, 2025). "qRT-PCR analysis revealed that TAMs cocultured with MMP28-knockdown cancer cells presented upregulated CD86 expression and downregulated CD163 expression." (PMID 39972459, 2025). "Conversely, CM derived from cancer cells overexpressing MMP28 demonstrated a significantly increased ability to recruit TAMs." (PMID 39972459, 2025). "To elucidate the underlying mechanism by which MMP28 mediates TAM chemotaxis and M2 TAM polarization within cancer cells, we explored potential intermediary factors." (PMID 39972459, 2025). "In contrast, TAMs cocultured with MMP28-overexpressing cancer cells displayed the opposite expression pattern." (PMID 39972459, 2025). "The secretion of IL-2, IL-5, IL-8, MCP-1, and VEGFA was significantly reduced in both the sh-MMP28-1 and sh-MMP28-2 AsPC-1 and BxPC-3 cancer cell lines." (PMID 39972459, 2025). "As regulatory targets of some ncRNAs, TSPOAP1, ADGRG6, MMP28 and other genes are particularly important in the initiation, progression of various cancers such as PC." (PMID 34809653, 2021). "We here demonstrate that, though hypermethylation of certain CpGs in promoter regions of the MMP2, MMP23B, MMP24, MMP25, and MMP28 genes is cancer specific, it lacks independent biological or clinical value, being rather a function from HER2 activation." (PMID 32397602, 2020). "Studies have shown that the expression of MMP-28 protein is increased in malignant tumors and cancer cell lines." (PMID 32596395, 2020). "Seven MMPs (MMP7, MMP11, MMP12, MMP13, MMP24, MMP27, and MMP28) had an AUC of greater than 0.95 for at least one cancer type." (PMID 31200666, 2019). "CYR61 and MMP28 are involved in functions such as cell proliferation, differentiation or metastasis related to the initiation and progression of cancer." (PMID 30819200, 2019). "In some tumors and cancer cell lines MMP28 expression is increased; although in some cases MMP28 protein is downregulated in cancer compared to normal tissues." (PMID 21615884, 2011). "MMP-28 is expressed at low levels in normal lung tissue, but the expression of MMP-28 is highly increased after cancer formation." (PMID 21843314, 2011). "The discrepancy between absence of activated MMP-28 in transfected nonmalignant COS-1 cells and CHO cells as compared to activated MMP-28 in transfected cancer cells cannot be readily explained." (PMID 21152186, 2011). "Compared with the control group, TAMs cocultured with MMP28 overexpressing (OE-MMP28) cancer cells presented 1833 differentially expressed genes (772 upregulated, 1061 downregulated), which are primarily involvedin TAM metabolic alterations, such as amino acid metabolism and glucose metabolism." (PMID 39972459, 2025). "Additionally, assessment of cell apoptosis revealed an increase in apoptosis upon MMP28 knockdown and a significant decrease upon MMP28 overexpression in both cancer cell lines." (PMID 39972459, 2025). "MMP-28, also known as epilysin, is downregulated in nine cancer types in our analysis." (PMID 31200666, 2019). "Interestingly, MMP2, MMP7, MMP23B, MMP27 and MMP28) are significantly down-regulated in seven to nine cancer types." (PMID 31200666, 2019).
cancer (continued). "In addition to MMP12 (present study), MMP1, MMP13 and MMP28 have also been shown to promote invasion and metastasis in various cancers." (PMID 24885469, 2014). "MMP-28, the most recently identified MMP, has been implicated in important biological and pathological processes including neuronal development, tissue repair, bacterial infection, and cancer." (PMID 21152186, 2011). "Our data demonstrate that MMP28 can act as an upstream regulator of EMT in vivo raising the possibility that other MMPs might have similar early roles in various EMT-related contexts such as cancer, fibrosis, and wound healing." (PMID 37590318, 2023). "Although much attention was paid to MMPs, it remained elusive what role MMP28 might play in cancer." (PMID 33761734, 2021). "Mechanistically, KLF9 inhibits the transcription of matrix metalloproteinase 28 (MMP28), a protein that facilitates cancer cell invasion." (PMID 40860800, 2025). "We demonstrated that modulating MMP28 expression altered the secretion of IL-8 and VEGFA by cancer cells, subsequently affecting TAM recruitment and M2 polarization." (PMID 39972459, 2025). "High levels of MMP28 promote the secretion of IL-8 and VEGFA by cancer cells by mediating the phosphorylation of the MAPK/JNK signalling pathway and then recruiting TAMs." (PMID 39972459, 2025). "Cytokine antibody array analysis revealed that MMP28 knockdown suppressed the production and release of IL-2, IL-5, IL-8, MCP-1, and VEGFA by cancer cells." (PMID 39972459, 2025). "The knockdown or overexpression of MMP28 altered the activity of the P38, ERK1/2, and JNK signaling pathways in the two cancer cell lines." (PMID 39972459, 2025). "Notably, JNK inhibition partially reversed the stimulatory effect of MMP28 on IL-8 and VEGFA secretion by these cancer cells." (PMID 39972459, 2025). "Notably, downregulation of zebrafish orthologues for MMP23B, MMP28, and CTSF are consistent with downregulated expression of these genes in several human cancer types." (PMID 39511408, 2025). "Considering previous reports on the relationship between MMPs and the efficacy of EGFR inhibitors, we believe that the correlation between MMP-28 and EGFR inhibitors in PDAC may be applicable to other cancers as well." (PMID 39994761, 2025). "Interestingly, while the MMPs members from MMP1 to MMP14 were generally upregulated in several cancer types, the others (MMP15 to MMP28) were downregulated." (PMID 34830271, 2021). "The signature genes, including CYR61, MMP28 and ACOX1, may play important roles in the initiation and progression of cancer." (PMID 30819200, 2019). "Overall, our results demonstrate a paracrine role for MMP28 in the EMT program of neural crest cells in vivo suggesting that such paracrine role might take place between other cells expressing MMPs such as fibroblasts and cancer cells." (PMID 37590318, 2023). "However, biological evidence from in vitro and in vivo experiments has not yet clarified the relationship between MMP28 and cancer metastasis." (PMID 21615884, 2011).
infection (2 papers, 2011 to 2022). The state of being infected such as from the introduction of a foreign agent such as serum, vaccine, antigenic substance or organism. "In vivo, STm infections results in transcriptional upregulation of MMPs family genes, Mmp3, Mmp8, and Mmp28 in PPs and mesenteric lymph nodes (mLNs) 2 days post-infection and further Mmp genes in the inflamed caecum up to 3 weeks post infection." (PMID 35733975, 2022). "This down-regulation of MMP28 by epithelial cells has been seen in other pulmonary infection models, and may be one mechanism by which host epithelial cells respond to infection." (PMID 22040290, 2011).
cardiovascular diseases (1 paper, 2020). "Our study provides some clinical evidence and data on the relevance of MMP-28 in cardiovascular diseases." (PMID 32596395, 2020).
degenerative diseases (1 paper, 2011). "All this data indicates that compared to other MMPs, MMP28 seems to be rather unresponsive to external inflammatory stimuli in disc cells, although being expressed in degenerative diseases that are characterized by inflammation." (PMID 21801383, 2011).
psychiatric diseases (1 paper, 2022). "Our results showed that MMP genes such as MMP-15, MMP-16, MMP-17, MMP-24 and MMP-28 were expressed highly or moderately in brain, implying the values in investigation of more genes in association with psychiatric diseases." (PMID 35444067, 2022).